RNU6-1134P (RNA, U6 small nuclear 1134, pseudogene)
Gene: Small nuclear RNA gene on chromosome 17 (31,713,753 to 31,713,853, forward strand). Ensembl gene ENSG00000202026.
Homologues: Orthologues: chimpanzee U6 (98% identical), dog U6 (77% identical), rat U6 (76% identical), guinea pig U6 (74% identical), mouse Gm24630 (71% identical), pig U6 (69% identical), rabbit U6 (69% identical), rat LOC120096101 (69% identical). Paralogues in human: RNU6-10P (81% identical), RNU6-1181P (81% identical), RNU6-633P (81% identical), RNU6-71P (81% identical), RNU6-949P (81% identical), RNU6-1024P (80% identical), RNU6-266P (80% identical), RNU6-348P (80% identical), RNU6-45P (80% identical), RNU6-46P (80% identical), RNU6-90P (80% identical), RNU6-1060P (79% identical), and 1284 more.